FGF14 (fibroblast growth factor 14)
Diseases named in the same sentence as FGF14 in open-access papers (continued):
Sharing a sentence is not in itself a finding about the gene and the disease.
colorectal cancer (5 papers, 2020 to 2024). A primary or metastatic malignant neoplasm that affects the colon or rectum. "Compared with normal tissue, primary colorectal cancer has reduced FGF14 expression, and significantly higher methylation of FGF14 has been observed in colorectal cancer." (PMID 37108717, 2023). "Very recently, Tianhong Su and colleagues extensively investigated the role of FGF14 in colorectal cancer cell lines." (PMID 34061869, 2021). "A similar effect of FGF14 overexpression on tumor size was recently shown in Balb/c nude mice in a colorectal cancer model." (PMID 32707902, 2020). "Based on our findings and the results of the other studies on FGF14 in the context of colorectal cancer and nasopharyngeal carcinoma, there is a strong evidence that FGF14 plays a role in tumor cell proliferation, migration, and invasion." (PMID 32707902, 2020). "A recent study on FGF14 in colorectal cancer reported tumor suppressive properties, which falls in line with our findings." (PMID 32707902, 2020). "FGF14 expression is altered in various tumors and it has been suggested to regulate apoptosis and proliferation in nasopharyngeal carcinoma and colorectal cancer." (PMID 32707902, 2020). "We identified that Fibroblast Growth Factor 14 (FGF14) was preferentially methylated in colorectal cancer (CRC)." (PMID 31949485, 2020). "Interestingly, they have suggested the tumor suppressor role of FGF14 in colorectal cancer." (PMID 34061869, 2021). "Moreover, FGF14 and SNX10 have demonstrated tumor suppressive properties in colorectal cancer." (PMID 38951817, 2024).
Friedreich ataxia (5 papers, 2023 to 2026). An inherited condition that affects the nervous system and causes movement problems. "Finally, in both post-mortem tissue and iPSCs-derived motoneurons, the FGF14 transcript and protein level were found to be significantly reduced compared to the controls, suggesting that GAA expansion might lead to a reduction in FGF14 transcription, similarly to Friedreich’s Ataxia." (PMID 38391932, 2024).
lung adenocarcinoma (5 papers, 2020 to 2023). A carcinoma that arises from the lung and is characterized by the presence of malignant glandular epithelial cells. "To further clarify the regulatory effect of miR-1246b on FGF14 in tumor cells, we detected the expression of miR-1246b and FGF14 in three lung adenocarcinoma cell lines, A549, H1299 and H1975." (PMID 38040694, 2023). "FGF14 has been confirmed to inhibit tumor growth in lung adenocarcinoma, and this effect can be achieved by the inhibition of COL11A1 and MUC16 proteins by FGF14." (PMID 38040694, 2023). "Two most recent studies reported that FGF14 overexpression leads to tumor suppressive effects in lung adenocarcinoma and nasopharyngeal carcinoma." (PMID 34061869, 2021). "FGF-14 is downregulated in lung adenocarcinoma patient samples, and the overexpression of FGF-14 in the lung adenocarcinoma cell line A549 results in downregulation of COL11A1 expression." (PMID 33668097, 2021). "Fibroblast growth factor-14 (FGF-14) is downregulated in lung adenocarcinoma patient samples, and its overexpression in the lung adenocarcinoma cell line A549 results in downregulation of COL11A1 expression." (PMID 35847935, 2022). "We analyzed lung adenocarcinoma (LUAC) patients samples and found that FGF14 was downregulated, correlating with reduced survival and oncogenic mutation status." (PMID 32707902, 2020).
lung carcinoma (5 papers, 2020 to 2024). "miR-1246b, which was extracted from BALF-EVs, targets FGF14 to promote lung cancer cell proliferation, migration and invasion." (PMID 38040694, 2023). "BALF-EVs carrying miR-1246b activate ERK and EMT by binding to FGF14, ultimately leading to the enhancement of lung cancer cell proliferation, migration and invasion." (PMID 38040694, 2023). "Further analyses found that with decreased FGF14 expression in lung cancer cells, the expression of p-ERK/ERK, N-cadherin, and Vimentin increased, but the expression of E-cadherin decreased." (PMID 38040694, 2023). "In contrast, FGF14 was highly expressed in a large cell carcinoma cell line (H460) and lung carcinoma (A427)." (PMID 32707902, 2020). "To restrain these findings, we performed additional experiments with H460 cells, a large cell lung cancer cell line that has a high baseline expression of FGF14." (PMID 32707902, 2020). "It appeared that FGF14 expression was reduced in the later stages of lung cancer and differed between the data sets." (PMID 32707902, 2020). "We investigated the role of FGF14 in lung cancer progression by first analyzing the mRNA expression of FGF14 in lung cancer samples from patients with LUAC." (PMID 32707902, 2020). "Collectively, these findings demonstrate that FGF14 overexpression markedly decreased the invasive potential of lung cancer cells in vitro." (PMID 32707902, 2020). "Previous studies have found that FGF14 can inhibit the proliferation of lung cancer cells." (PMID 38040694, 2023). "The results of CCK-8 and EdU assays showed that after inhibiting the expression of FGF14 in lung cancer cells, the proliferation rate of tumor cells significantly increased, and the wound healing assay results demonstrated that the migration ability of lung cancer cells was enhanced." (PMID 38040694, 2023). "Subsequent mechanistic studies showed that miR-1246b inhibited the expression of FGF14 in lung cancer cells, further leading to ERK phosphorylation and epithelial-to-mesenchymal transition (EMT), which ultimately contributed to lung cancer cell proliferation, migration and invasion." (PMID 38040694, 2023). "We also examined the expression of FGF14 in human lung cancer cell lines." (PMID 32707902, 2020). "In addition, we used the same experimental setup and also detected these phenotypes in other lung cancer cell lines H838 and H460, which have a high basal expression of FGF14." (PMID 32707902, 2020). "FGF14 overexpression in lung cancer cell lines resulted in decreased proliferation, colony formation, and migration, as well as increased expression of epithelial markers and a decreased expression of mesenchymal markers, indicating a mesenchymal to epithelial transition in vitro." (PMID 32707902, 2020). "Nonetheless, the role of FGF14 in lung cancer, especially in NSCLC remains unelucidated." (PMID 32707902, 2020). "By inhibiting the fibroblast growth factor 14 (FGF14), miR-1246b promotes the proliferation, migration, invasion, EMT, and ERK phosphorylation of lung cancer cells." (PMID 39598229, 2024).
Parkinson disease (5 papers, 2009 to 2026). A progressive degenerative disorder of the central nervous system characterized by loss of dopamine producing neurons in the substantia nigra and the presence of Lewy bodies in the substantia nigra and locus coeruleus. "We identified pathogenic FGF14 GAA repeat expansions in five individuals with Parkinson's disease and one control subject." (PMID 41327893, 2026). "A similar proportion of cerebellar-predominant and parkinsonism-predominant multiple system atrophy cases had FGF14 expansions." (PMID 40239008, 2025). "However, future studies comparing MSA patients with other neurodegenerative conditions, such as Parkinson's disease and dementia with Lewy bodies, could help to explore whether FGF14 expansions are uniquely associated with MSA or are part of a broader neurodegenerative spectrum." (PMID 40239008, 2025). "Pathogenic GAA repeat expansions in FGF14 are an established cause of late-onset cerebellar ataxia, but have not been linked to Parkinson's disease." (PMID 41327893, 2026). "Pathogenic GAA repeat expansions in FGF14 are an established cause of late-onset cerebellar ataxia, but have not been linked to Parkinson’s disease (PD)." (PMID 40894141, 2025).
channelopathies (4 papers, 2019 to 2025). "However, less is known about the interplay between these kinases and FGF14 in regulating Nav1.2 function—a gap in knowledge that could be particularly relevant in the context of Nav1.2 channelopathies, which have been implicated in the incidence of neurodevelopmental disorders." (PMID 39125637, 2024).
depression (4 papers, 2016 to 2025). "Fgf14-/- mice showed increased expression of cannabinoid receptor without alterations of dopaminergic system in mPFC, suggesting a link between Fgf14 and endocannabinoid system in the control mechanisms underlying depression." (PMID 40204701, 2025). "Recently, Fgf14 has been genetically associated to depression." (PMID 40204701, 2025). "Additionally, SNPs in FGF14 have been associated with dependence on alcohol and illegal substances in humans, and a fine-mapping study found several SNPs to be associated with major depressive disorder in a study of Dutch twins." (PMID 28469558, 2017). "This study demonstrates that female Fgf14-/- mice are resilient to depression, as reported by reduced level of despair behavior, anhedonia, and increased sociability." (PMID 40204701, 2025). "Our findings suggest that Fgf14 is involved in stress-coping mechanisms and could be targeted to improve resilience to depression." (PMID 40204701, 2025). "GSK3β directly phosphorylates FGF14 at S226 and Nav1.6 at T1936, two sites that were found to be disease-related in experimental models of neurodegeneration and of vulnerability to stress and depression, respectively." (PMID 31729429, 2019).
multiple system atrophy (4 papers, 2023 to 2025). Multiple system atrophy (MSA) is a neurodegenerative disorder characterized by autonomic failure (cardiovascular and/or urinary), parkinsonism, cerebellar impairment and corticospinal signs with a median survival of 6-9 years. "Seven multiple system atrophy patients had a pathogenic FGF14 GAA≥300 expansion (five pathologically confirmed and two clinically diagnosed), and 12 had intermediate GAA250–299 expansion (six pathologically confirmed and six clinically diagnosed)." (PMID 40239008, 2025). "Partial phenotypic overlap has been suggested between multiple system atrophy and spinocerebellar ataxia 27B, the autosomal dominant ataxia caused by an intronic GAA•TTC repeat expansion in FGF14." (PMID 40239008, 2025). "We identified 19 multiple system atrophy cases carrying an FGF14 GAA≥250 expansion (2.89%, n = 19/657), a significantly higher frequency than in controls (1.40%, n = 12/1003) (P = 0.04)." (PMID 40239008, 2025). "Therefore, screening for FGF14 GAA•TTC repeat expansion should be considered for multiple system atrophy patients with rapid loss of mobility and for complete diagnostic accuracy at inclusion in disease-modifying multiple system atrophy drug trials." (PMID 40239008, 2025). "In this study, we investigated the frequency of FGF14 GAA•TTC repeat expansion in clinically diagnosed and pathologically confirmed multiple system atrophy cases." (PMID 40239008, 2025).
nasopharyngeal carcinoma (4 papers, 2020 to 2021). A carcinoma arising from the nasopharyngeal epithelium. "Interestingly, a recent study revealed that FGF14 is repressed in patients with nasopharyngeal carcinoma, and FGF14 overexpression suppresses cell proliferation." (PMID 33083023, 2020). "In fact, whenever FGF14 was downregulated, such as in LUAC, colorectal, and nasopharyngeal cancer, it correlates with decreased OS." (PMID 32707902, 2020).
paroxysmal dyskinesia (4 papers, 2017 to 2025). Paroxysmal dyskinesia (PD) is a rare heterogenous group of movement disorders manifesting as abnormal involuntary movements that recur episodically and last only a brief time. "Disruption of FGF14 in the fgf14−/− experimental model also leads to paroxysmal dyskinesia and ataxic gait attributed to dysfunction of GABA signalling in the basal ganglia that are remarkably similar to the motor features of SCA27 and paroxysmal hyperkinesias in some FGF14 mutations." (PMID 32112487, 2020).
Alzheimer disease (3 papers, 2017 to 2025). A progressive, neurodegenerative disease characterized by loss of function and death of nerve cells in several areas of the brain leading to loss of cognitive function such as memory and language. "Functional enrichment of single nucleotide polymorphisms (SNPs) in patients with type-II diabetes and Alzheimer’s disease shows that FGF14 is significantly overrepresented in these two diseases because of its phosphorylation by JNK." (PMID 28469558, 2017). "Changes in the mRNA expression of MAPK/JNK signaling proteins, including FGF14, are also significantly overrepresented in early-onset Alzheimer’s disease patients." (PMID 28469558, 2017). "Taken together, these results indicate that the interaction between JNK and FGF14 might be an important area for future research in Alzheimer’s disease." (PMID 28469558, 2017).
epilepsy (3 papers, 2013 to 2024). A brain disorder characterized by episodes of abnormally increased neuronal discharge resulting in transient episodes of sensory or motor neurological dysfunction, or psychic dysfunction. "The intracrine FHF4 (FGF14 according to the old nomenclature) also seems to be involved in the morpho-functional alterations associated with epilepsy." (PMID 24062643, 2013).
Limb ataxia (3 papers, 2023 to 2025). A kind of ataxia that affects movements of the extremities. "All patients in the FGF14-GAA-positive cohort were diagnosed with gait and appendicular ataxia." (PMID 39801711, 2025).
pancreatic cancer (3 papers, 2021 to 2023). "Of note, a recent study reported that FGF12 (the homologue of FGF14) have a malignancy- inhibitor effect on pancreatic cancer cell lines." (PMID 34061869, 2021). "In future, preclinical studies are required to establish the therapeutic relevance of FGF14 in pancreatic cancer." (PMID 34061869, 2021). "Previously, the dysregulation of FGF14 using pancreatic cancer cell lines was reported." (PMID 34061869, 2021). "Furthermore, multivariate analysis also revealed FGFR1 and FGF14 as independent prognostic markers for better overall survival in pancreatic cancer patients." (PMID 34061869, 2021). "In KRAS‐mutant pancreatic cancer cohort (n = 133), a strong correlation between PLK1 and FGF9, FGF14 was observed, and in KRAS‐mutant colon cancer (n = 170), only FGF14 strongly correlated with PLK1." (PMID 34369083, 2021).
autism (2 papers, 2019 to 2025). Persistent deficits in social interaction and communication and interaction as well as a markedly restricted repertoire of activity and interest as well as repetitive patterns of behavior. "Although protein–protein interaction data are far from complete, this suggests that Snap25 and Aldh1a1 may be key players in the pathogenesis observed in Fgf14−/− mice and perhaps SZ and/or autism." (PMID 30678040, 2019). "Furthermore, genetic variants of SNAP25 leading to low protein expression levels have been associated with hyperactivity and/or with low cognitive scores in autistic patients, corroborating our results linking differentially expressed proteins in Fgf14−/− mice with autism." (PMID 30678040, 2019).
autonomic dysfunction (2 papers, 2024 to 2025). "However, unlike SCA27B, the majority of MSA patients carrying an FGF14 GAA≥250 repeat expansion reported here experienced early and severe gait ataxia and significant autonomic dysfunction, including neurogenic bladder and orthostatic hypotension from the disease onset." (PMID 40239008, 2025).
microcephaly (2 papers, 2019 to 2020). A congenital or acquired developmental disorder in which the circumference of the head is smaller than normal for the person's age and sex. "Small deletions are associated with either normal IQ or mild ID, but neither microcephaly nor dysmorphism has been described in conventional FGF14 mutations." (PMID 32112487, 2020).
tauopathy (2 papers, 2019 to 2023). Neurodegenerative disorders involving deposition of abnormal tau protein isoforms (tau proteins) in neurons and glial cells in the brain. "The authors noticed that deletion mutation of Fgf14 may cause and/or accelerate tauopathy-like phenotypes in rTg4510 mice and cautioned against the use of rTg4510 mice for drug screening." (PMID 37152607, 2023). "In our lab, we attempted a human tau transgene knock-in into the Rosa26 locus to generate a novel tauopathy mouse without any mutation in the Fgf14 gene." (PMID 37152607, 2023). "Furthermore we show that the tauopathy-like phenotype seen in rTg4510 requires a ~70-copy tau-transgene insertion in a 244 kb deletion in Fgf14, a ~7-copy tTA-transgene insertion in a 508 kb deletion that disrupts another five genes, in addition to high transgene overexpression." (PMID 31171783, 2019).
alcoholism (1 paper, 2019). "Of particular note are the enriched pathways in male Fgf14−/−mice, which includes alcoholism, drug addiction, and related pathologies." (PMID 30678040, 2019).
aspiration pneumonia (1 paper, 2025). "Future studies should include detailed assessment of the severity of cerebellar involvement and related complications, such as dysphagia, aspiration pneumonia and increased frequency of early falls, in MSA cases with FGF14 expansions and their impact on survival." (PMID 40239008, 2025).
Brain atrophy (1 paper, 2024). Partial or complete wasting (loss) of brain tissue that was once present. "This is particularly relevant because functional knockout of FGF14 may contribute to accelerated neuronal loss and brain atrophy in tetO-MAPT*P301L-Fgf14 models, and thus it cannot be assumed that mutant tau, alone, drives the reported changes in neurodegeneration." (PMID 38750510, 2024).
CAEBV infection (1 paper, 2006). "Eventually, we found several genes with expression levels significantly higher in cell lines established from NK/T-cell lymphoma than those from CAEBV infection: FGF14, PDCD4, PCNA, MAP2K4, ITGAX and AKAP2 were preferentially expressed in SNK/T cells established from nasal NK/T lymphoma." (PMID 16449999, 2006).
developmental delay (1 paper, 2025). "Intellectual disability and developmental delay have been reported in several cases of FGF14 deletions, with almost complete penetrance (90%)." (PMID 41099962, 2025).
glioma (1 paper, 2016). A benign or malignant brain and spinal cord tumor that arises from glial cells (astrocytes, oligodendrocytes, ependymal cells). "The RTK ligands including EFNB2, SEMA3D, PDGFA, SEMA3A and FGF14 were amplified in ~5% of the RMPAhigh gliomas." (PMID 27385209, 2016).
Intellectual disability (1 paper, 2025). "However, isolated FGF14 exon 4–5 deletion is sufficient to cause intellectual disability." (PMID 41099962, 2025).
liver fibrosis (1 paper, 2019). "We did not identify direct reports of the role of FGF14 in hepatic fibrosis, but the FGF11-14 subfamily members interact with mitogen-activated protein kinase (MAPK)." (PMID 31031647, 2019). "We speculated that FGF14 is related to the synthesis and degradation of collagen and ECM in the hippocampus, based on the functions of FGF in the liver fibrosis model." (PMID 31031647, 2019).
malaria (1 paper, 2023). Malaria is a serious and sometimes fatal disease caused by a parasite that commonly infects a certain type of mosquito which feeds on humans. "Overall, these studies highlight a novel cytokine signaling response converging on FGF14 that contributes to neuronal and systemic effects of malaria, with mechanistic insight that is applicable to a broad array of neuroinflammatory conditions." (PMID 38115011, 2023).
oesophagitis (1 paper, 2021). "The inflammation-related variants associated with oesophagitis were rs4772468 at FGF14 (associated with increased risk) and rs270771 at LILRP2 (associated with decreased risk)." (PMID 33810047, 2021). "Two SNPs replicated their association with radiation-induced oesophagitis (rs7165790 located in the BLM gene: odds ratio (OR) = 0.16, 95% CI = 0.04–0.65, p-value = 0.010; rs4772468 at FGF14: OR = 4.36, 95% CI = 1.15–16.46, p-value = 0.029)." (PMID 33810047, 2021).